CD36 (CD36 molecule (CD36 blood group))
Diseases named in the same sentence as CD36 in open-access papers (continued):
Sharing a sentence is not in itself a finding about the gene and the disease.
atherosclerosis (continued). "The most studied scavenger receptors are cluster of differentiation 36 (CD36), SR-A, and lectin-like oxLDL receptor-1 (LOX-1), all of which have been shown to contribute to foam cell formation and atherosclerosis, at least in part." (PMID 37378396, 2023). "On the other hand, CD36 deficiency, diagnosed as having type 1, based on a lack of uptake of 15-(p-iodophenyl)-3-R,S-methyl-pentadecanoic acid in myocardia, might cause extensive atherosclerosis leading to acute myocardial infarction." (PMID 37239003, 2023). "Apart from FA, CD36 also recognizes and interacts with oxidized LDL (oxLDL), which eventually progresses atherosclerosis." (PMID 36769293, 2023). "This review identified CHI3L1, CD36, LEPR, RETN, IL-18, RBP-4, and RARRES2 genes as the potential genetic markers of IR and atherosclerosis in T2DM patients with CAD." (PMID 36984867, 2023). "Many studies have shown that CD36, LPL, FADS1, and SCD1 promoted atherosclerosis development by regulating lipid metabolism." (PMID 37324939, 2023). "TMAO enhanced the expression of CD36/MAPK/JNK pathway, promoting foam cells formation and, ultimately, atherosclerosis." (PMID 35448889, 2022). "In vitro, Mφs stimulated with IL-13 increased the uptake of oxLDL by CD36 upregulation and induced the expression of the lipid exporter (ABCA1), preventing foam cell formation, which is a major driver of atherosclerosis." (PMID 35488301, 2022). "In conclusion, our study demonstrated that EEEG decreased CD36-mediated ox-LDL uptake and macrophage foam cell formation ultimately inhibited atherosclerosis." (PMID 36505350, 2022). "Further evidence has illustrated that SRs, such as CD36 (also known as platelet glycoprotein IV), perform most of the ox-LDL uptake by macrophages, which is the first step of atherosclerosis that leads to the formation of foamy macrophages." (PMID 36110563, 2022). "Quercetin prevents the development of atherosclerosis in ApoE−/− mice by regulating the expression of PCSK9, CD36, PPARγ, LXRα, and ABCA1." (PMID 35845584, 2022). "The genes that were differentially expressed in the lipid and atherosclerosis pathway were APOB (P = 0.008), CD36 (P = 0.040), CALM1, CALM2, CALM3 (P = 0.015), and HSPA8 (P = 0.047)." (PMID 36506940, 2022). "TheNrf2-mediated role in potentiating atherosclerosis also involves NLRP3inflammasome activation, decreased uptake of acetylated LDL, and up-regulatedexpression of CD36 scavenger receptor in macrophages." (PMID 39077721, 2022). "However, some Dual PPARα/γ agonist such as compound 3q may accelerate atherosclerosis, it may related to the increase expression of the vascular endothelial activation and inflammation markers, such as P-selectin, MCP-1, VCAM-1, and CD36, that are also associated with plaque complexity." (PMID 35309069, 2022). "These extracellular vesicles, including exosomes, facilitate atherosclerosis via specific proteins, such as ROS-producing NADPH oxidase and LDL-scavenging CD36." (PMID 33921168, 2021). "Like CD36, LOX1 can also bind oxLDL, and ApoE−/− mouse model research indicated that LOX1 overexpression dramatically enhanced atherosclerosis." (PMID 34539804, 2021). "As expected, we observed that laminar shear stress induces cell shape change, up‐regulates vasoprotective genes (such as CPY1B1, THBD and NOS3) and, however, down‐regulates pro‐atherosclerosis genes (such as VCAM1, CD36, and ANGPT2)." (PMID 34085389, 2021). "ox-LDL is the initiating molecule in the process of atherosclerosis, which can be combined with macrophage scavenger receptors such as CD36, SR-A1 and SR-A2, SR-BI, MARCO, LOX-1, and PSOX to boot inflammation and promote atherosclerosis." (PMID 32733941, 2020).
atherosclerosis (continued). "CD36 and CD47 not only regulate the inflammatory process in atherosclerosis but also regulate angiogenesis in the process of atherosclerosis." (PMID 32733941, 2020). "While CD36 binds modified oxLDL, LOX-1 interacts with other, moderately modified LDL forms, and can therefore be important at early stages of atherosclerosis development." (PMID 31717832, 2019). "CD36, a scavenger receptor, recognizes amyloid β and oxidized LDL, which contribute to pathogenesis of AD and atherosclerosis, respectively." (PMID 31312197, 2019). "The expression of positive regulators of atherosclerosis (ABCA1, ABCG1) was higher in the P group than that in the RP group (P < 0.05), and the opposite effect was observed for negative regulators (ACAT1, CD36)." (PMID 30105261, 2018). "Recent advances on the emerging role of CD36 and GHRP hexarelin in regulating PPARγ downstream actions with benefits on atherosclerosis, hepatic cholesterol biosynthesis and fat mitochondrial biogenesis are summarized here." (PMID 29883404, 2018). "Our results showed that overexpression of salusin-α increased the expression of positive regulators of atherosclerosis (ABCA1 and ABCG1) and inhibited negative regulators of atherosclerosis (ACAT1 and CD36)." (PMID 30105261, 2018). "In atherosclerosis, ox-LDL binding to CD36 results in a positive feedback loop via activation of peroxisome proliferator activated receptor gamma (PPARγ)." (PMID 29896109, 2018). "To further validate the anti-atherosclerosis effect of QSYQ, we next performed western blotting analyses in whole aorta to determine the protein expression of CD36." (PMID 29137256, 2017). "CD36 was a scavenger receptor on the surface of macrophage that binded oxidized LDL and contributed to the pathogenesis of atherosclerosis." (PMID 29137256, 2017). "OxLDL has been shown to induce Cxcl1 expression in macrophages via a co-operation of CD36/TLR4/TLR6, and CXCL1 represents a key mediator of leukocyte recruitment in atherosclerosis." (PMID 26947073, 2016). "Indeed, it is not surprising that the genetic deletion of either SR‐A1 or CD36 has no beneficial effects in ApoE‐deficient mice 38, 39 because oxLDL uptake by macrophages could be compensated by SR‐BI (in early atherosclerosis) and LOX‐1." (PMID 26493158, 2016). "As another limitation, we explored atherosclerosis-related gene expression at mRNA level only, except for CD16 and CD36, which were analyzed by flow cytometry." (PMID 25875611, 2015). "The relative contributions of CD36, SR-A and LOX-1 to the diabetes-induced enhancement of foam cell and atherosclerosis formation by DCs has to be clarified by future studies." (PMID 23718574, 2013). "Elevated glucose can increase the expression of scavenger receptors CD36, SR-A and LOX-1 in macrophages, thereby contributing to diabetes and its related disease atherosclerosis." (PMID 23718574, 2013). "High glucose concentrations have been reported to enhance the levels of CD36, SR-A, and LOX-1 receptors involved in LDL internalisation, and the role of these receptors in the development of atherosclerosis is well established." (PMID 21904540, 2011). "Therefore, CD36 is also termed as multi-ligand scavenger receptor and one of the important pathologic functions of scavenger receptors, related to foam cell formation and the pathogenesis of atherosclerosis, is recognition and internalization of oxidatively modified LDL." (PMID 19604372, 2009). "This can be explained, in part, by the fact that PPARγ agonist stimulate expression of the scavenger receptor CD36 in macrophages that facilitates uptake of oxidized LDL and contributes to the development of atherosclerosis." (PMID 18485218, 2008). "CD36+ ECs, VEGFA+ macrophages, and adventitial fibroblasts play critical roles in atherosclerosis." (PMID 40594772, 2025). "Additionally, FXR activation downregulates the expression of CD36 and ABCA1 in macrophages, leading to decreased cholesterol uptake, thus preventing atherosclerosis." (PMID 40076864, 2025).
atherosclerosis (continued). "Targeting CD36, UCHL1 or USP11 using small molecule inhibitors or reverse genetic strategies could provide new strategies to target both atherosclerosis and cancer." (PMID 40563926, 2025). "Thus, KGs of NK cells for hawthorn's effects on the PVAT microenvironment of atherosclerosis were JUN, CXCR4, CD36, GNLY, and FABP4." (PMID 40824771, 2025). "Mice lacking CD36 have been reported to show increased insulin sensitivity, decreased inflammation in adipose tissue and resistant to the development of atherosclerosis." (PMID 39911578, 2024). "Furthermore, butyrate treatment of Ea.hy926 cells has been found to reduce ox-LDL uptake, CD36, VCAM-1, TNF-α, and interleukin-1β/6 production while increasing IL-10 production, suggesting its potential as a treatment for atherosclerosis." (PMID 39275259, 2024). "A recent in vivo study demonstrated that deleting Trpm2 or inhibiting TRPM2 activity in cultured macrophages suppressed the CD36 signaling cascade induced by oxidative low-density lipoprotein and TSP1, suggesting that TRPM2 is an effective therapeutic target for atherosclerosis." (PMID 39039680, 2024). "Second, reductions in monocyte CD36 expression and monocyte uptake of modified LDL with LSFD may further decrease foam cell formation and therefore may also contribute to atherosclerosis prevention." (PMID 37325398, 2023). "In addition, CD36, JAK2, STAT3, and CDC42 are essential in reducing lipid accumulation and atherosclerosis in foam cells." (PMID 36903257, 2023). "Therefore, circEZH2 promoted cholesterol synthesis and uptake to enhance foam cell formation and atherosclerosis development by regulating the miR-217-5p/KLF5/DHCR24 axis, miR-133b/SQLE axis, and miR-378b/CD36 axis." (PMID 37324939, 2023). "After overlapping the 431 putative targets of atorvastatin with 15 common pathogenic genes between atherosclerosis and NSCLC, then find 4 genes (MMP9, MMP12, CD36, and FABP4) were identified as potential therapeutic targets of atorvastatin for atherosclerosis and NSCLC." (PMID 37978381, 2023). "CD36 is recognized to be involved in the uptake of ox-LDL by monocytes and macrophages, leading to the formation of foam cells, which plays its part in atherosclerosis." (PMID 37228156, 2023). "Therefore, circEZH2 promoted cholesterol synthesis and uptake to foam cell formation and atherosclerosis development by regulating the miR-133b/SQLE axis and miR-378b/CD36 axis." (PMID 37324939, 2023). "It was reported that targeted deletion of scavenger receptors, CD36, and scavenger receptor-A in hypercholesterolemic mice inhibits the pathogenesis of atherosclerosis without altering oxidized LDL uptake in macrophages." (PMID 36105534, 2022). "The results showed that quercetin regulated lipid metabolism by up-regulating the expressions of PPARγ, LXR-α, ABCA1, and down-regulating the expressions of PCSK9 and CD36, reducing the content of TC, LDL-C, oxLDL, and lipid droplets in the cytoplasm, and alleviated the symptoms of atherosclerosis." (PMID 35399657, 2022). "We were interested in how atherosclerosis would develop in the absence of EC CD36, because high-fat diets promote atherosclerosis in part through changes in shear stress and other pro-inflammatory pathways." (PMID 34888367, 2021). "LYN is the src family gene, and it is revealed that the scavenger receptor CD36 could bind to the oxidized LDL, thus activating LYN by the recruitment of Na/K-ATPase-LYN complex and enhancing the development of atherosclerosis." (PMID 34688276, 2021). "Indeed, beyond its effects on LDL metabolism, several studies have demonstrated the existence of additional roles of PCSK9 in different stages of atherosclerosis through its interaction with other receptors, such as LRP1, ApoER2, and CD36." (PMID 34070931, 2021). "CD36 is better recognized as a scavenger receptor, as it mediates the uptake of ox-LDL by macrophages and the formation of foam cells during arterial atherogenesis to promote atherosclerosis." (PMID 32733941, 2020).
atherosclerosis (continued). "Animal, which is genetic deletion of CD36 expression, exhibits decreased foam cell formation and induces the negative effect on the development of atherosclerosis in apo E−/− mice." (PMID 32801299, 2020). "PETIC may have a protective effect on obesity and atherosclerosis by regulating the expression of PPARγ, LXRα, ABCA1, SR-A1, CD36, and NF-κB." (PMID 33261070, 2020). "Our study concluded that UCHL1 deletion decreases foam cell formation by promoting the degradation of CD36 protein, indicating UCHL1 may be a potential target for atherosclerosis treatment." (PMID 32801299, 2020). "Furthermore, CD36 and ox‐LDL binding can activate signalling pathways, including those of protein kinases that lead to the development of atherosclerosis." (PMID 32851768, 2020). "CD36 was also reported to activate NLRP3 inflammasome in response to atmospheric particulate matter exposure, as well as modulating lipid accumulation in macrophage, ultimately contributing to the progression of atherosclerosis." (PMID 33008402, 2020). "Double knockout of SR-A and CD36 in APO-E-null mice did not reduce aortic root atherosclerosis compared with APOE-null mice; however, the authors did not study SR-A- or CD36-null mice in isolation." (PMID 33182772, 2020). "CD36 signalling responds to ox-LDL, and on the one hand, reduces macrophage motility and probably induces the trapping of macrophages in the arterial intima, which promotes atherosclerosis." (PMID 31109109, 2019). "Different from increased CD36 and activated NLRP3 inflammasome induced by LDL and ox-LDL in atherosclerosis and foam cell formation, high-level triglycerides and FFAs conduct CD36-mediated lipid accumulation, NLRP3 inflammasome activation, and podocyte injury of ORG." (PMID 31097920, 2019). "Furthermore, our study indicates that SPP1, CD36, ATP6V0D2, CHI3L1, MYH11, and BDNF, which showed favorable diagnostic performance and high correlations with several clinical biochemical parameters, may potentially serve as biomarkers to diagnose and monitor the prognosis of atherosclerosis." (PMID 31682178, 2019). "Our findings indicated that myricetin suppressed cholesterol accumulation in macrophage foam cells by inhibition of CD36-mediated ox-LDL uptake, and suggested myricetin may have an important therapeutic function for atherosclerosis." (PMID 31049071, 2019). "This might elucidate the potential of CD36 and BLTR1 bearing MMV phenotypes as novel biomarkers in predicting atherosclerosis." (PMID 30425991, 2018). "This demonstrates that low ratio of n-6 to n-3 inhibits the formation of the foam cells as the quantity of cholesterol uptake via CD36 and biosynthesis via ACAT1 is less than the cholesterol efflux via ABCA1, which co-regulate to inhibit the development of the atherosclerosis." (PMID 29801502, 2018). "In ApoE−/− mice, the absence of CD36 protects them from the development of atherosclerosis and lesion complexity." (PMID 28084332, 2017). "CD36 is a membrane glycoprotein present in mononuclear phagocytes, adipocytes, hepatocytes and myocytes, is also involved in the uptake of oxidized LDL, apoptotic cells and in the modulation of inflammation, atherosclerosis, diabetes, and cardiomyopathy." (PMID 27977792, 2016). "Nevertheless, our findings that LDL was identified to be an opsonin to enhance CD36 mediated phagocytosis of GAS by monocyte and whole human blood may provide clues for anti-GAS infection and atherosclerosis prevention strategies." (PMID 26392394, 2016). "Here the authors show that TREM-1 plays an important role in atherosclerosis, a chronic and non-infectious disease, by critically skewing myelopoiesis towards preferential monocyte differentiation and by contributing to CD36-driven cellular lipid accumulation." (PMID 27762264, 2016).
atherosclerosis (continued). "CD36 is also a fatty acid translocase that is involved in fatty acid uptake and esterification in macrophages; thus, CD36 is regarded as important in foam cell formation during the progression of atherosclerosis." (PMID 27400732, 2016). "Because the human periodontal disease pathogen, Porphyromonas gingivalis (Pg), interacts with innate immune receptors Toll-like Receptor (TLR) 2 and CD36/scavenger receptor-B2 (SR-B2), we studied how CD36/SR-B2 and TLR pathways promote Pg-mediated atherosclerosis." (PMID 25938460, 2015). "CD36 is a glycoprotein and binds to collagen, thrombospondin, anionic phospholipids and oxidized LDL contribute to important pathological processes highly relevant to atherosclerosis and thrombosis." (PMID 26709509, 2015). "A recent study revealed that soluble CD36 in plasma correlates significantly with markers of atherosclerosis, insulin resistance and fatty liver in a non-diabetic healthy population." (PMID 24766787, 2014). "The present study shows that high glucose can mediate upregulation of SR-A, CD36 and LOX-1, which could be related to initiation and progression of atherosclerosis in diabetes patients." (PMID 23718574, 2013). "In addition, CD36 is a receptor for oxidized LDL and plays a role in scavenging LDL modified by oxidation and mediating the atherosclerosis process." (PMID 23249574, 2012). "In line with this hypothesis, previous studies with MSR1 and CD36-knockout mice showed that disruption of each receptor pathway partially inhibited the uptake of modified LDL in macrophages and retarded atherosclerosis progression in a similar manner." (PMID 22470565, 2012). "During atherosclerosis monocyte-derived macrophages accumulate cholesteryl esters from low-density lipoproteins (LDLs) via lectin-like oxidised LDL receptor-1 (LOX-1) and class AI and AII (SR-AI, SR-AII) and class B (SR-BI, CD36) scavenger receptors." (PMID 21904540, 2011). "Gene-deletion and bone marrow–transplantation experiments have provided evidence that macrophages scavenger receptor A and CD36 exert non dispensable effects in mediating the uptake of oxidized LDL by macrophages and promoting the development of atherosclerosis." (PMID 20949026, 2010). "Ganoderic acid A (GAA) prevents ox-LDL-induced macrophage inflammation and lipid deposition in THP-1 cells by blocking Notch1/PPARγ/CD36 signaling, which may provide a theoretical framework for the clinical application of GAA in the treatment of atherosclerosis." (PMID 40099271, 2025). "Thus, mice without functional CD36/ApoE exhibit significant atheroprotection in various models of atherosclerosis, which reflects the effect of reduced CD36 levels on HDL holoparticle uptake." (PMID 39965658, 2025). "Induced inflammation in atherosclerosis activates the ROS/NF-κB/LOX-1/oxLDL axis, upregulating the expression of PCSK9, which further upregulates LOX-1 to induce the transformation of macrophages and VSMCs into foam cells, and CD36 to induce platelet activation and thrombosis." (PMID 39941130, 2025). "Furthermore, CD36, a high-affinity receptor for oxidized LDL (ox-LDL), is widely expressed in various cell types and plays a critical role in lipid metabolism, inflammation, and atherosclerosis." (PMID 41357244, 2025). "The clinical significance of these CD36 negative macrophages remains unclear, but their absence in atherosclerotic plaques suggests that they may play a protective role in atherosclerosis‐free tissue." (PMID 40496346, 2025). "Given that cholesterol crystals are endogenous activators of inflammasomes, oxidized LDL taken up via CD36 might form crystals rather than be esterified, thereby activating inflammasomes and exacerbating atherosclerosis." (PMID 39911578, 2024). "FAT/CD36 function in a wide range of processes not always related to FAs uptake, translocation, and oxidation, as apoptosis, angiogenesis, phagocytosis, thrombosis, inflammation, and atherosclerosis." (PMID 36615118, 2022).